MYC (MYC proto-oncogene, bHLH transcription factor)
Diseases named in the same sentence as MYC in open-access papers (continued):
Sharing a sentence is not in itself a finding about the gene and the disease.
tumor (continued). "In this trial, among the secondary endpoints, associations between c-MYC expression in tumor tissue (prespecified) and genetic alterations in circulating tumor DNA (retrospective) with clinical outcomes were also evaluated." (PMID 38927637, 2024). "At the same time, BETi-induced inhibition of MYC increased the total level of nuclear p21, promoting tumor suppressive action of p21 in PTEN-deficient CRC cells." (PMID 38617536, 2024). "MYC, a transcription factor-encoding oncogene, is widely recognized for its role in driving tumor cell proliferation and metabolic reprogramming across various cancer types." (PMID 39883338, 2024). "Simply activating MYC in tissue culture is sufficient to induce many of the characteristics associated with tumour cells." (PMID 38637125, 2024). "We thus became interested in CAMKV, which was previously correlated to a worse NB patient survival and whose mRNA expression is highly associated to that of MYCN or MYC in NB cell lines and primary tumor samples." (PMID 38255303, 2024). "MYC is the human homolog of the oncogene (v-myc) carried by the avian retrovirus, which is associated with myelocytomatosis and other neoplasms." (PMID 38932267, 2024). "More than half of patients with HGSOC exhibit MYC oncogenic pathway activation, and MYC amplification is associated with tumor recurrence." (PMID 39135097, 2024). "The pathways involved in the neuroendocrine-low differentiation of SCLC tumors, including YAP1, NOTCH, Wnt family (WNT), and MYC, have each been implicated in tumor progression and treatment resistance across various cancers." (PMID 39456533, 2024). "MYC also represses innate immunity through its effect in promoting tumor-associated macrophages (TAMs)." (PMID 37450923, 2024). "MYC is an oncogenic transcription factor, overexpressed in many malignancies and linked to aggressive tumor progression and poor survival outcomes." (PMID 39497821, 2024). "Noted that MYC is upregulated in tumor-associated macrophages (TAMs), which is involved in suppressing immunosurveillance." (PMID 38390324, 2024). "This TSD phenotype involves the activation of the MYC-HIF2α pathway and, importantly, is linked to a hypoxic tumor microenvironment." (PMID 39963656, 2024). "In the HBx dysregulated HBV-HCC pathways, this panel of MIRNAs can influence a number of genes in the TGF-B/SMAD pathway by targeting validated gene targets like TGFBR1/SMAD3/, CDKN1A and MYC to influence both oncogenesis and the loss of tumor suppression." (PMID 38256049, 2024). "In particular, pathological activation of MYC results in uncontrolled tumor growth, whereas strategies that inhibit MYC, either directly or indirectly, have been shown to cause a significant reduction in tumor size." (PMID 39615685, 2024). "MYC is overexpressed in approximately 70% of malignancies, induces tumor progression and is associated with poor prognosis." (PMID 38821916, 2024). "Deregulated MYC expression acts as a driver of both tumor initiation and maintenance and it is linked to all the defining hallmarks of cancer." (PMID 39457457, 2024). "The coworking network between PEG10 and MYC promotes that Smad2/3 and Snail are translocated into the nucleus, which is known to be a hallmark for the beginning and maintenance of tumor growth, survival and migration." (PMID 38204280, 2024). "We concluded that high MYC expression causes tumour cells to depend on the complete RUVBL1 protein function." (PMID 38821858, 2024). "In summary, our results showed that USP1 deficiency downregulated c-MYC, which promoted tumor growth in vivo." (PMID 39513905, 2024). "So far, only a few target genes associated with eIF5A hypusination have been reported in tumor cells, such RhoA and MYC." (PMID 38654332, 2024).
tumor (continued). "MYC also functions in cell invasion and is associated with several prognostic signatures involved in tumor invasion and metastatic growth." (PMID 37450923, 2024). "When searched within the hallmark gene sets, the up-regulated proteins were also found to be enriched in the MYC (proto-oncogene) target V1 and V2 gene sets, which are known to be associated with tumour aggressiveness." (PMID 38052461, 2024). "Ambra1 also participates in autophagy signaling and its deficiency leads to tumor hyperproliferation through MYC hyperphosphorylation, thereby causing tumorigenesis." (PMID 37450923, 2024). "It has been reported that BTYNB decreases the association of IGF2BP1 with MYC RNA and E2F-driven RNA while inhibiting the proliferation of several tumor cells." (PMID 39534570, 2024). "We provide compelling evidence that Cdk12 is a tumor suppressor gene and demonstrate its loss promotes androgen receptor (AR) and MYC-mediated hypertranscription, transcription-replication conflicts (TRCs), and resultant DNA damage." (PMID 39368479, 2024). "The analysis indicated that lactylation played vital roles in pro-tumor pathways like “MYC,” “PI3K-AKT-mTOR,” “HYPOXIA” and was associated with immune-related pathways such as “INTERFERON_GAMMA_RESPONSE”, “IL2_STAT5_SIGNALING” and “TGF_BETA_SIGNALING”." (PMID 38419085, 2024). "Examination of 50 hallmark gene sets across the tumour cell clusters revealed that Cluster3 was particularly enriched in cell cycle pathways such as MYC, E2F and G2M, supporting its identification as a subgroup of early‐differentiating tumour cells." (PMID 39054572, 2024). "This negative regulation of MYC expression together with the fact that mutations in the PVT1 promoter frequently occur in human cancers suggest a rather tumor suppressive role for the PVT1 locus and promoter in human cancers." (PMID 37782337, 2024). "Silencing MYC in multiple tumor models leads to tumor regression associated with remodeling of the tumor microenvironment." (PMID 38424044, 2024). "This miRNA is primarily known as a tumour suppressor that influences the expression of various oncogenic pathways, particularly those associated with c-MYC, and is downregulated in various cancers." (PMID 38541714, 2024). "Upon MYC downregulation, loss of “don’t find me” signals enables residual tumor cell destruction and sustained regression." (PMID 38730256, 2024). "MCR-loss tumours exhibited relatively increased MYC expression levels intermediate between PMN-hit and WT cases." (PMID 38877600, 2024). "By targeting various components of the TCF-4-Wnt/β-catenin-MYC-PD-L1 pathway, new diagnostic and therapeutic strategies can be developed to enhance the immune defence against tumours." (PMID 39735605, 2024). "Tumors eventually relapsed despite retreatment with TAM; their molecular analysis showed that all contained an unfloxed VkMYC allele, highlighting the selection of MYC expression for tumor growth." (PMID 38714690, 2024). "Our findings indicate that the increased cohesion due to the deletion or mutation of the E242-E261 region in MYC correlates with increased expression of its target genes and enhanced tumor cell proliferation." (PMID 39343006, 2024). "Several oncogenic events, such as KRAS mutation or MYC activation, have also been shown to suppress or evade anti-tumour immune responses via immune checkpoint molecules." (PMID 37761948, 2023). "Co-targeting MYC and CHEK1 activities synergistically inhibits CTDNEP1-deficient MYC-amplified tumor growth and prolongs animal survival." (PMID 36765089, 2023). "These caused a dramatic alteration in the FLX1 transcriptome, resulting in downregulation of Hallmark MYC Targets gene sets and upregulation of inflammatory and tumor suppressive gene sets." (PMID 36692000, 2023).
tumor (continued). "Most of the eIF4E-sensitive mRNAs have a long and highly structured 5’UTR region, and these mRNAs encode many proteins associated with cell proliferation and tumor progression, including MYC, VEGF, cyclin, and others." (PMID 36830614, 2023). "We found patients in high-risk score group was significantly enriched in E2F targets, MYC targets V1 and MYC targets V2, which are relevant to tumor cell differentiation, proliferation, and metabolism." (PMID 36869083, 2023). "This decrease in MYC expression led to a concomitant decrease in tumor cell viability in vitro, with the associated epigenetic marks detectable at the sites of interest 2 weeks post-administration." (PMID 36631803, 2023). "The HC2/ABC-MB cases were most enriched in “MYC targets v1” and “MYC targets v2” pathways, both of which have been associated with tumor aggressiveness and proliferation." (PMID 37333202, 2023). "Suppression of RUVBL1 leads to attenuated tumor growth, loss of histone H4 acetylation, and ablated MYC signaling." (PMID 37075745, 2023). "MYC activation or overexpression has been shown to induce genomic instability that is linked to tumor initiation including tumorigenesis in murine G3-MBs from cerebellar progenitor cells." (PMID 36765089, 2023). "Additional studies demonstrated that inactivation of c-MYC resulted in tumor regression and was associated with cellular differentiation and apoptosis in transgenic mouse models." (PMID 38078012, 2023). "Compared with the control group, the mice implanted with OE-REG1α cells showed faster tumor formation and a remarkable increment of tumor growth and weight, whereas cells with MYC deficiency counteracted these effects." (PMID 37626036, 2023). "MYC proteins are implicated in a range of tumor-promoting activities including cell proliferation, dedifferentiation and stemness, angiogenesis, migration, invasion, immune evasion and therapy resistance." (PMID 36575316, 2023). "Amplification of the 8q24 region and overexpression of MYC is seen in both high-grade premalignancy and invasive tumors and is associated with poor outcome in different human tumor types, including OS." (PMID 37279073, 2023). "Conversely, unveiling the metabolic traits of MYC-high clones in situ would enable us to devise new therapeutic strategies targeted at the metabolism underlying malignant tumor progression." (PMID 37946084, 2023). "Differential expression analyses between tumor and normal tissue revealed the MYC targets V2 hallmark gene set as most significantly upregulated in tumor samples (q-value < 0.0001)." (PMID 36977461, 2023). "Since Sirt2−/− HCCs were more differentiated and had fewer proliferative and immunological markers than Sirt2+/+ HCCs, a loss of Sirt2 resulted in a lesser HCC tumor grade 36 days post-c-MYC induction." (PMID 37628798, 2023). "The transcription factor MYC is overexpressed in many human cancers and has a significant causal role in tumor incidence and progression." (PMID 37908640, 2023).
tumor (continued). "By inspecting their oncoprint, 27/59 tumours harboured mutations in either SOX9 or MYC and were wild-type in either BRAF, KRAS or NRAS, hinting towards an alternative cetuximab resistance mechanism." (PMID 37666855, 2023). "The expression level of GLS is regulated by the oncogene c-MYC, and its upregulation is a hallmark of tumor growth." (PMID 37190124, 2023). "Inclusion of HRAS exon 5 is found to negatively correlate with MYC hallmark enrichment in the majority of 27 tumor types." (PMID 37399401, 2023). "The upregulation of mTOR and MYC implicates these classic oncogenic signaling paradigms as mechanisms for growth in a tumor with mtDNA mutations and chromosomal losses." (PMID 37262067, 2023). "Genetic studies have shown that suppressing the activation of c-MYC can cause tumor regression by inhibiting proliferation and inducing apoptosis." (PMID 38003498, 2023). "The present review focuses on HIF- and MYC signaling in both neoplasms and discusses the interaction of associated pathways during neural crest and adrenal development as well as potential consequences on tumorigenesis." (PMID 37361539, 2023). "Loss of MYC led to complete tumor clearance and cure of these mice, confirming that these tumors are oncogene addicted." (PMID 36869047, 2023). "Surprisingly, tumor regression associated with tumor microenvironment remodeling occurs when MYC expression is silenced in multiple tumor models." (PMID 36966168, 2023). "While for a long time, c-MYC overexpression has been associated with tumor progression and aggressiveness in HCC, recent studies have shown its implication in cHCC-CCA development." (PMID 37627221, 2023). "Deregulated expression of MYC proteins can cause uncontrolled cell proliferation and tumor development." (PMID 37370649, 2023). "We find the MYC oncogene causally regulates Siglec ligand production to enable tumor immune evasion." (PMID 36897988, 2023). "To examine the clinical relevance of our findings, we evaluated the association between MYC amplification status and mTORi response in tumor samples derived from patients with cancer." (PMID 37642941, 2023). "The pervasive nature of MYC proteins in cancer is linked to their ability to regulate the expression of genes associated with core tumor processes, a function that is dependent on the heterodimerization of MYC with its obligate cofactor MAX." (PMID 37336886, 2023). "Pathways associated with treatment resistance and tumor invasion (e.g., Hypoxia, G2M, MYC, EMT) were significantly upregulated in the high-risk group." (PMID 36817452, 2023). "Pathway analysis with Hallmark genes showed that DNA repair, cell cycle, MYC targets, E2F targets, and heme metabolism were enriched in tumor samples (adjusted P < 4.5e-08)." (PMID 37414763, 2023). "To investigate how MYC is linked to an immune-suppressive phenotype, we performed RNA-seq on two different sources of tumor cells." (PMID 36323660, 2022). "In this context, MYC also controls the activation of tumor-associated macrophages, which increase cancer's aggressiveness, and regulates the expression of epithelial-to-mesenchymal transition (EMT) effectors." (PMID 36860495, 2022). "While these genes are strongly expressed in early PGCs to ensure a hypomethylated epigenome, their expression is downregulated or largely abrogated in MYC tumor subtypes suggesting a deficiency of active demethylation." (PMID 35318328, 2022). "In concordance with our in vitro findings, MUC1 expression in single SCLC tumor cells was significantly associated with activation of the HALLMARK MYC TARGETS V1 gene signature." (PMID 35612556, 2022).
tumor (continued). "Together, our results suggest that EMT is associated with reduced but intermediate response to Erlotinib whereas repression of ZEB1 signature and upregulation of MYC signature is associated with tumor-type agnostic resistance at the Pan-cancer scale." (PMID 35618721, 2022). "A possible role of cell competition has been suggested in field cancerization, a phenomenon characterized by phenotypic and genetic changes in tumor neighboring cells, and MYC-mediated “super competition” has been implicated in tumor progression." (PMID 36140779, 2022). "We also observed gains of 13, 15, 16, 20, and loss of 17 and 19 late in disease progression of MYC+ tumor cases." (PMID 36051032, 2022). "c-MYC inhibition has been demonstrated to cause sustained tumour regression through the promotion of proliferative arrest, differentiation, apoptosis and cellular senescence in cancer cells." (PMID 35267559, 2022). "MYC inhibitors induce immunogenic cell death in tumor cells and cause increased T cell infiltration and subsequently upregulate PD-L1 in the tumor microenvironment." (PMID 36510584, 2022). "On the other hand, tumor cells absorb glucose and glutamine from the extracellular media due to mutations in key metabolic regulatory genes, including c-MYC, AKT, and PI3K." (PMID 36483029, 2022). "Analysis of hallmarks of cancer in patients with early disease onset within the TCGA cases, revealed the enrichment of gene sets associated with tumor aggressiveness such as the hallmarks of MYC targets, mTOCRC1 and TGFß-signaling." (PMID 36352274, 2022). "Enhanced anti-tumor efficacy was also associated with a more pronounced reduction in the mRNA level of the known ER target MYC in tumor tissue, suggesting enhanced engagement of the ER transcriptional network." (PMID 35353838, 2022). "Previous studies show aberrant MYC signaling is associated with increased polyamine synthesis, contributing to the deregulation of tumor metabolism and increased tumorigenesis." (PMID 36139061, 2022). "This further suggests the importance of MYC signaling in mediating the tumor immunosuppressive microenvironment.Moreover, the association of MYC with immune checkpoints is also slowly being revealed." (PMID 36299592, 2022). "In a cancer cell adapted to cope with high levels of DNA replication stress, due to the activation of oncogenes such as MYC, for example, there appears to be an intimate association with tumour development and the increased rate of replication origin firing." (PMID 36240067, 2022). "We found that multiple classic tumor-related pathways were enriched in the high-risk group, such as “hypoxia,” “MYC targets,” and “cancer poor survival” pathways." (PMID 36698888, 2022). "In this study, we found for the first time that the MYC targeting gene MAD2L1 is associated with PCa bone metastasis tumor cell dormancy." (PMID 35305591, 2022). "c-MYC is overexpressed in many neoplastic diseases, either due to mutation of its gene or due to the induction of its expression by a number of upstream oncogenic pathways." (PMID 36818371, 2022). "He found that in the models that had MYC overexpression, there was a dramatic decrease in lymphocyte infiltration into the tumours, along with immune signature loss." (PMID 36242657, 2022). "Downregulation/deletion of sirtuin 6 (SIRT6), a known repressor of tumor driver MYC is associated with adenoma formation and increased glycolysis during all stages of colorectal adenomas." (PMID 36618350, 2022). "Enriched pathways present in the circle-associated transcriptome of most samples were metabolic and well-known cancer-related pathways; specifically, the MSigDB hallmark pathway for MYC targets was enriched in every tumor." (PMID 35565439, 2022).